MTOR (mechanistic target of rapamycin kinase)
Diseases named in the same sentence as MTOR in open-access papers (continued):
Sharing a sentence is not in itself a finding about the gene and the disease.
Obesity (continued). "Dysregulation of mTOR signaling has also been shown to play a role in the context of obesity." (PMID 38892329, 2024). "This increase in placenta phospholipids may be related to low-grade placental inflammation in pregnancies complicated by obesity and could contribute to accelerated fetal growth due to the activation of the mTOR signaling pathway by phospholipids." (PMID 39275250, 2024). "In addition, overnutrition mediates obesity and triggers mTOR chronic hyperactivation in various tissues, promoting IR, hyperlipidemia, inflammation, stress and vasoconstriction." (PMID 39200267, 2024). "Overall, one could conclude, mTOR mediates metabolic syndrome and obesity-induced inflammation that is exaggerated by inhalation exposure." (PMID 38711460, 2024). "Indeed, increased expression of placental mTOR has been shown in GDM, especially when associated with obesity." (PMID 36830073, 2023). "Obesity reciprocally induces a hyperactivation of the mTOR pathway." (PMID 37626871, 2023). "Notably, obesity and overnutrition trigger chronic hyperactivation of mTOR activity in multiple tissues." (PMID 37250653, 2023). "Notably, the PI3K/Akt/mTOR signaling pathway is also one of the signaling mediators of obesity-related factors and has thus become the focus of obesity and cancer." (PMID 37954072, 2023). "The PI3K/Akt/mTOR signaling pathway is a key pathway linking obesity and cancer." (PMID 37954072, 2023). "Only a few studies investigated the mTOR pathway in ADHD, but both the mTOR and Wnt pathways are implicated in cellular metabolism and energy balance, and emerging data suggests a positive association between ADHD, obesity, and T2DM." (PMID 36875654, 2023). "The potential therapeutic effects of leucine supplementation have been examined in a various scenario, as a dietary supplement for the treatment of obesity and type 2 diabetes, due to leucine’s ability to affect a variety of physiological processes through mTOR and perhaps other signaling pathways." (PMID 38046946, 2023). "Consequently, these findings suggest that mTOR inhibition should be considered a treatment approach to prevent BC recurrence in women with obesity." (PMID 37512149, 2023). "The AMPK/mTOR signaling pathway may be involved in lipid metabolism or promote autophagy in obesity depression." (PMID 38248829, 2023). "The attenuation of the obesity-induced upregulation of miR-96 and its target mTOR might also contribute to GSE-mediated metabolic improvements in obesity." (PMID 37686829, 2023). "Obesity and an overabundance of amino acids can trigger the hyperactivation of the mTOR pathway, which in turn could support SARS-CoV-2 replication by utilizing the mechanisms involved in host viral replication and subsequent inflammation." (PMID 35711466, 2022). "Targeting mTOR signaling by dietary polyphenols is a novel mechanism in obesity prevention." (PMID 36501200, 2022). "AZI has been reported to affect mTOR signaling and the autophagy process, which may potentially contribute to the development of obesity 49-51." (PMID 35154482, 2022). "Regardless of whether polyphenols modulate signal pathways or gut microbiota, mTOR seems to be the important target of the anti-obesity effect." (PMID 36501200, 2022). "Overactivation of S6K/mTOR pathway contributes to several diseases such as diabetes and obesity." (PMID 36465704, 2022). "Studies have shown that the methylation rate of the TSC1 promoter in the hypothalamus of obese rats is significantly increased, and inhibition of this methylation downregulates the expression of mTOR, thereby activating autophagy in the hypothalamus and alleviating the obesity phenotype." (PMID 36313328, 2022). "Because the mTOR pathway is on the center of cell growth and metabolism, comprehensively understanding this pathway will contribute to the therapy of related diseases, including cancers, type 2 diabetes, obesity, and neurodegeneration." (PMID 35740927, 2022).
Obesity (continued). "Importantly, we further investigate the possible downstream targets of mTOR that EA against obesity." (PMID 36313328, 2022). "Additional pathways that take place in obesity are the Ghre/AMPK/mTOR pathways." (PMID 36362220, 2022). "However, currently, we cannot conclusively attribute a role of mTOR activation by insulin on reducing protein breakdown in muscle of humans with obesity." (PMID 35350688, 2022). "In fact, activation of mTOR in the fasted-state is higher in muscle of humans with obesity." (PMID 35350688, 2022). "Anhydroicaritin could be used as a specific molecule to target and inhibit the activation of SREBPs through the LKB1/AMPK/mTOR pathway, thereby improving diet-induced obesity." (PMID 36501200, 2022). "Using mouse models of diet-induced obesity, they performed transcriptional analysis on NK cells which unveiled the upregulation of lipid metabolism-related genes and the downregulation of genes involved in the cytotoxic response and the mTOR signaling pathway." (PMID 36569860, 2022). "Finally, Spearman's correlation analysis revealed that the high levels of mTOR were significantly correlated with weight (p = 0.044), BMI (p = 0.010), obesity grade (p = 0.013), and Kellgren-Lawrence grade (p < 0.001)." (PMID 36035226, 2022). "First, we couldn’t fully determine the role of mTOR/PPAR-γ pathway in the development of obesity, as an initiator or a responsor." (PMID 35135573, 2022). "Hence, disruption of mTOR signaling can be potential factor contributing to dysregulated protein metabolism in skeletal muscle of humans, including those with obesity." (PMID 35350688, 2022). "Meanwhile, researches suggested that obesity-related IR might impede skeletal muscle growth and accelerate muscle protein degradation by impairing the mTOR pathway." (PMID 36387941, 2022). "In a high-fat-diet-induced obesity mouse model, 20 or 200 mg/kg bw of lychee fruit extract (oligonol) was administered by gavage for 6 weeks, and the results showed that oligonol prevented weight gain in mice and decreased mTOR activity." (PMID 36501200, 2022). "We restricted a genetic window of analysis to components of a metabolically relevant pathway, the mTOR pathway, due to its involvement in the sensing of energy, nutrients, and stress, as well as growth factors, and its deregulation in the obesity state." (PMID 36316722, 2022). "However, growing evidence indicates that the anti-obesity effects of dietary polyphenols are involved in the mTOR signaling pathway." (PMID 36501200, 2022). "Furthermore, we identified a group of candidate microRNAs including miR-103–3p preventing PI3K-Akt-mTOR pathway over-activation and thus protecting against hyperphagic obesity induced by Dicer1 deletion in the mouse hypothalamus." (PMID 35490865, 2022). "Additional models will be required to differentiate the effects of upregulated mTOR signaling in central vs peripheral Nav1.8 lineage neurons on altering affect and metabolism and their consequences for the onset of the normal weight obesity phenotype." (PMID 36586433, 2022). "Because activation of mTOR inhibits autophagy in skeletal muscle, obesity-induced chronic activation of mTOR may explain the lower protein breakdown observed in muscle of humans with obesity." (PMID 35350688, 2022). "Publications indicate that dietary polyphenols exert anti-obesity effects via targeting mTOR." (PMID 36501200, 2022). "We concluded that improving tissue hypoxia or enhancing autophagy through the AMPK/mTOR/p70S6K pathway may be a relevant strategy for improving obesity- and ageing-related disorders." (PMID 36188454, 2022). "Both vitamin D and obesity have been reported to affect the mTOR pathway." (PMID 33670988, 2021). "In diabetes and obesity, excess insulin, branch chain amino acids, and ATP activate mTOR." (PMID 34987473, 2021).
Obesity (continued). "Studies using mouse models have shown that mTOR inhibitors block the tumor-enhancing effects of obesity, indicating that mTOR inhibitors in combination with intermittent fasting could represent a potential strategy for breaking the obesity-BC link." (PMID 33815289, 2021). "mTOR is closely related to obesity and plays a vital role in regulation of energy metabolism." (PMID 34335285, 2021). "Whether the state of insulin and/or mTOR signaling is already altered (i.e., by obesity) needs further studies compared to healthy lean subjects with normal insulin sensitivity." (PMID 34956089, 2021). "Although the precise mechanistic explanations for the alteration in the number and population of CD4+ T cells seen with obesity remain unclear, mTOR activation by increased leptin may be involved." (PMID 33670988, 2021). "mTOR signaling is the most essential intracellular mechanism that coordinates local nutrition availability and systemic energy status, and its dysregulation is related to obesity and type 2 diabetes." (PMID 34944525, 2021). "We assessed whether energy expenditure could account for the obesity phenotype in female mTOR-KOPlacenta mice." (PMID 34032632, 2021). "Adult female mTOR-KOPlacenta mice display exacerbated obesity phenotypes under HFD challenge." (PMID 34032632, 2021). "The mTOR pathway plays critical roles in mammalian metabolism and physiology through activity in many tissues, including liver, muscle, brown adipose tissue and the brain, and has been found to be dysregulated in diabetes and obesity." (PMID 33806509, 2021). "Our objective was to link obesity-ADS induction of LAT1 to the induction of mTOR signaling." (PMID 34201429, 2021). "The pathogenesis of BC in obesity is stimulated by mTOR hyperactivity." (PMID 34201429, 2021). "In addition, activation of the mammalian target of rapamycin (mTOR) signaling pathway has also been shown to inhibit autophagy in high-fat diet-induced obesity and metabolic syndrome." (PMID 34831481, 2021). "In the present study, we tested the hypothesis that placental mTOR regulates fetal birth weight as well as the development of obesity and T2D in the adult offspring." (PMID 34032632, 2021). "These novel findings suggest that inhibiting mTOR by targeting LAT1 could be particularly relevant for ER-positive BC in obesity." (PMID 34201429, 2021). "Given that leucine can stimulate and sustain mTOR activation, increased levels of this amino acid could in turn contribute to sustained mTOR hyperactivity in obesity." (PMID 34201429, 2021). "A report shows that whole-body Atf4-KO mice are resistant to age-related and diet-induced obesity because of the reduction in the mammalian target of rapamycin (mTOR) signaling and expression of the gene that regulates the intracellular concentration of amino acids." (PMID 34547510, 2021). "As obesity may affect both gene and protein expression in tumors, we focus on the latter because the mTOR pathway signaling is primarily through post-translational protein phosphorylation." (PMID 33024820, 2020). "Data from patients suffering from obesity and T2D showed reduced activity of mammalian target of rapamycin (mTOR), and lower insulin receptor substrate 1 (IRS1) levels in adipocytes from subcutaneous fat with higher autophagy activation compared with nondiabetic patients." (PMID 32015340, 2020). "An obesity-related signaling pathway is a mechanistic Target of Rapamycin (mTOR) pathway." (PMID 33024820, 2020). "Conversely, postprandial or obesity-associated activation of MAFG would trigger energy-demanding, anaplerotic processes like an increase in cellular proliferation and protein synthesis as a consequence of mTOR-4E-BP1 pathway activation." (PMID 32005828, 2020). "In addition to that, mTOR signals in women having obesity/ gestational diabetes mellitus (GDM), given birth to larger babies and in animal models related to overgrowth of the fetus." (PMID 33414718, 2020).
Obesity (continued). "Moreover, obesity has been proven to reduce the activity of the mTOR pathway and lead to endothelial dysfunction in vasculature of animal models of obesity." (PMID 32907629, 2020). "Significantly, mTOR is activated through several mechanisms in obesity." (PMID 33105727, 2020). "Altogether, our study revealed that Notch3 promotes adipocytic differentiation of 3T3‐L1 pre‐adipocytes cells by up‐regulating LARS expression and activating the mTOR pathway, which might be an emerging target for obesity treatment." (PMID 31755192, 2020). "Accumulating evidence suggests that mTOR signalling could be a key regulator of obesity and its morbidities." (PMID 32191726, 2020). "Autophagy is regulated by the integrated action of insulin and mTOR, both altered in obesity." (PMID 31130916, 2019). "Within macrophages, we identified metabolic pathways regulated by miR-146a that could contribute to its protective role during DIO, and show that blockade of mTOR using rapamycin could reverse the obesity phenotype in miR-146a-/- mice." (PMID 30768595, 2019). "IRS1 mSer612 and mSer632/635 have been cited as negative regulatory sites for IRS1 signaling through tyrosine phosphorylation, and mSer1097, regarded as a potential mammalian target of rapamycin (mTOR) /S6K signaling pathway, is activated in the liver of model animals of obesity." (PMID 31426549, 2019). "The mTOR pathway mediates effects of obesity due to HFD in mammals." (PMID 30781653, 2019). "It is suggested that mTOR signaling may be a key pathway connecting obesity and endometrial cancer, which needs to be verified in a clinical trial." (PMID 31440472, 2019). "This might be closely associated with abnormal increase of mTOR activation-mediated severe oxidative stress and neuroinflammation in the hippocampal CA1 in pre- and/or post-ischemic phases under obesity’s conditions." (PMID 31546722, 2019). "Positive energy balance, overnutrition and obesity can produce a hyperactivity of mTOR pathway via PI3k/Akt activation, may activate mTORC1/S6K and reduce AMPK activity." (PMID 31337351, 2019). "Major downstream pathways of AMPK, such as the sterol regulatory element-binding transcription factor 1 (SREBF1, also known as SREBP1) pathway related to lipogenesis and the mechanistic target of rapamycin (mTOR) pathway, whose activation contributes to obesity, were downregulated by GTE." (PMID 31500159, 2019). "In this second scenario, obesity represents only a side effect of the excess nutrient status and the fulcrum are the cellular nutrient sensing pathways; see for example the possible central role of mTOR." (PMID 31130916, 2019). "Therefore, the link of disabled mTOR pathway to metabolic diseases, and promising strategies of inhibiting mTOR in the prevention and treatment of obesity and its comorbidities should be considered." (PMID 30621146, 2019). "Nevertheless, greater basal mTOR phosphorylation may prevent the characteristic postprandial increase in mTOR phosphorylation in those with obesity, perhaps suggesting an upper limit for activation of anabolic signaling through this protein complex." (PMID 31263701, 2019). "Deregulation of mTOR’s enzymatic activity has roles in cancer, obesity, and aging." (PMID 30326670, 2018). "The control of mTOR activity has interest in cancer, obesity, and aging." (PMID 30326670, 2018). "In that situation, Leu exacerbation of mTOR signaling could be the linking mechanism between early feeding and adult obesity." (PMID 29329236, 2018). "A recent study suggested a beneficial effect of mTOR by mediating the anti-obesity effects of fibroblast growth factor 21 (FGF21), implying complex pathways linking obesity and ageing which may involve negative feedback mechanisms." (PMID 28957990, 2018).
Obesity (continued). "The aberrant insulin receptor signaling that occurs as a result of obesity, including Akt and mTOR signaling, is known to alter cell proliferation and growth and may mediate progressive changes in the epigenetic control of genes related to the cell cycle." (PMID 29952094, 2018). "Altogether, these findings suggest anethole may provide an anti-obesity signal by regulating cellular metabolism through ROS and mTOR." (PMID 29980168, 2018). "Moreover, the mTOR signaling pathway regulates many major biological processes and is related to many pathological conditions such as cancer, obesity, type 2 diabetes, and neurodegeneration." (PMID 29686696, 2018). "IL-6 activates transcription factor STAT3, phosphorylates Jun-(N)-terminal Kinase (JNK) and ERK, indirectly alters AKT and mammalian target of rapamycin (mTOR)-S6K signaling, and ultimately promotes hepatocarcinogenesis in an obesity-induced chronic inflammatory microenvironment." (PMID 29492237, 2018). "Additionally, hyperinsulinemia which often accompanies obesity stimulates the mechanistic target of rapamycin (mTOR), whose blockade results in prolonged lifespan in mice." (PMID 28957990, 2018). "Obesity and over-nutrition induce a chronic hyper-activation of mTOR activity in multiple tissues." (PMID 30011848, 2018). "Inhibition of Akt-mTOR signaling protects from obesity and extends life span in animals." (PMID 28316325, 2017). "Gene expression studies on hNAG-18 have shown that GDF-15 may influence age-associated pathology development through mechanisms related to obesity, appetite, insulin sensitivity, energy metabolism and mTOR activity." (PMID 27734214, 2017). "Mechanistically, the obesity-related inflammation includes mTOR, JAK, JNK, IKKβ, and PI3K/Akt signaling pathways involved in inflammation activation, which contribute to increased secretion of cytokines, such as TNF-α, IL-6, and resistin, and decreased secretion of adiponectin." (PMID 28182687, 2017). "This is in keeping with the hypothesis that obesity-induced hyperactive Akt-mTOR signaling contributes to premature aging and reduced self-renewal capacity of ASCs while WL inhibits this pathway and hence protects ASCs." (PMID 28316325, 2017). "Optimal doses and schedules of administration could be selected by administration of pan-mTOR inhibitors to prevent obesity in mice on high fat diet (HFD)." (PMID 28077803, 2016). "Therefore, the objective of this study was to investigate the effect of exercise and dietary change on obesity and insulin resistance and mTOR signaling protein levels in skeletal muscle of obese rats induced by high fat diet for 15 weeks." (PMID 27508151, 2016). "S6K1, downstream of mTOR, protects against age- and diet-induced obesity in mice." (PMID 27244896, 2016). "Activation of mTOR promotes obesity, and obesity, in turn, activates mTOR." (PMID 26053184, 2015). "This gene was previously known for its roles in mammalian target of rapamycin (mTor) signaling, but its role in obesity development was unknown." (PMID 25825681, 2015). "This speculation follows from studies showing that inhibition of the PTEN/mTOR pathway provides protection against many pathologies including neurodegenerative diseases, cancer, heart diseases, obesity and kidney disease." (PMID 24671191, 2014). "Because obesity is a condition with increased nutrient availability, we hypothesized that diet‐induced obesity activates placental mTOR signaling." (PMID 24744907, 2014). "Since our group has previously identified TEFF cells as key players in adipose tissue inflammation, ERK and mTOR inhibitors might elicit a similar anti-inflammatory effect in obesity." (PMID 24904823, 2014). "In the fat tissue, mTOR promotes adipocyte differentiation and hypertrophy, increases lipogenesis (synthesis of triglycerids) and decreases lipolysis (hydrolysis of triglycerides), leading to fat accumulation or obesity." (PMID 25476900, 2014).